YTHDF1 (YTH N6-methyladenosine RNA binding protein F1)
Diseases named in the same sentence as YTHDF1 in open-access papers (continued):
Sharing a sentence is not in itself a finding about the gene and the disease.
lung squamous cell carcinoma (7 papers, 2021 to 2022). "YTHDF1 deficiency could affect the translation efficiency of CDK2, CDK4 and cyclin D1 and inhibit NSCLC cell proliferation and lung squamous cell carcinoma progression, while high YTHDF1 expression was associated with better clinical outcome." (PMID 36118041, 2022). "In lung squamous cell carcinoma, YTHDF1 is significantly negatively correlated with PD-L1, PD-1, PD-L2, CTLA-4, TIGIT, VISTA, and TIM3." (PMID 36479088, 2022). "In lung squamous cell carcinoma, the low YTHDF1 group was also mainly enriched in immunity-related signaling pathways (allograft rejection, IL2-STAT5 signaling, inflammatory response, IL6-JAK-STAT3 signaling, and TNFA signaling via NFKB and interferon gamma response)." (PMID 36479088, 2022).
oral squamous cell carcinoma (7 papers, 2020 to 2025). "METTL3 facilitates oral squamous cell carcinoma tumorigenesis by strengthening the c‐Myc stability via YTHDF1‐mediated m6A modification." (PMID 34151473, 2021). "Additionally, METTL3 could enhance the stability of c-MYC through YTHDF1-mediated m6A modification and promote tumorigenesis in oral squamous cell carcinoma." (PMID 36675186, 2023). "Accordingly, in oral squamous cell carcinoma, METTL3 can collect the m6A reader YTHDF1 to facilitate their target c-MYC transcript stability." (PMID 37259333, 2023). "This multi-layered regulation is absent in oral squamous cell carcinoma, where YTHDF1-mediated regulation of c-MYC is limited to mRNA stability without evidence of translational coordination or nuclear export involvement." (PMID 41167308, 2025).
thyroid cancer (7 papers, 2021 to 2024). "YTHDF1 was elevated in 14 of the 17 tumors but reduced in thyroid carcinoma (THCA), Kidney renal clear cell carcinoma (KIRC) and Kidney chromophobe (KICH)." (PMID 37833468, 2023). "However, YTHDF1 mRNA expression was low only in THCA (thyroid carcinoma)." (PMID 34026603, 2021). "However, YTHDF1 was lowly expressed in thyroid carcinoma than normal samples." (PMID 34434939, 2021). "We showed that METTL14, FTO, and ALKBH5 were down-regulated in most cancers, whereas YTHDF1 and IGF2BP3 were up-regulated in 12 cancer types except for thyroid carcinoma (THCA)." (PMID 33718187, 2021).
viral infection (7 papers, 2016 to 2024). "During viral infection, loss of YTHDF1 exhibited the antiviral activities following with the enhanced IFN responses." (PMID 34324489, 2021). "Overall, these data confirm our previous results that YTHDF1-3 proteins bind to m6A-modified HIV-1 genomic RNA during viral infection." (PMID 28901284, 2017). "Considering that SFTSV replicates in the cytoplasm where m6A-binding proteins YTHDF1/2/3 locate, and that YTHDF1/2/3 broadly promote virus infection in an m6A-dependent manner, we reasoned that YTHDF1/2/3 proteins may have a similar impact on the SFTSV lifecycle." (PMID 39585899, 2024). "The partial knockdown of YTHDF1 or YTHDF3 in Jurkat cells increased HIV-1 infection by three- to four-fold (p<0.005), while YTHDF2 knockdown slightly increased viral infection at 24 hpi." (PMID 27371828, 2016). "Among m6A readers, YTHDC1 was upregulated by viral infection (three of six experiments), while the expression levels of YTHDF1 and YTHD2 were not affected." (PMID 34502037, 2021). "Based on the results that the antiviral effects of YTHDF1 knockdown were not completely recovered by overexpression of ADAR1p150, there could be other m6A-regulated ISGs that are responsible for the effects of YTHDF1 knockdown upon viral infection." (PMID 34324489, 2021). "Meanwhile, knocking down YTHDF2, but not YTHDF1 and YTHDF3, was conducive to the viral infection and replication." (PMID 33510385, 2021).
asthma (6 papers, 2021 to 2025). "YTHDF1, identified as a significant modulator of airway inflammation in asthma, augments the translation of CLOCK in an m6A‐dependent manner." (PMID 41473388, 2025). "Here, present research indicated that a novel m6A reader YTHDF1 also significantly up-regulated in the asthma cellular model." (PMID 36992945, 2023). "In conclusion, our research utilized the PDGF-induced ASMCs to investigate the function and mechanism of YTHDF1 in asthma." (PMID 36992945, 2023). "This study unveiled a novel finding that m6A reader YTHDF1 play acritical role in asthma airway remodeling, involving ASMCs proliferation and migration abilities." (PMID 36992945, 2023). "However, the deletion of CLOCK abrogates these inflammatory phenotypes, indicating the integral role of CLOCK in the YTHDF1‐mediated inflammatory response in asthma." (PMID 41473388, 2025). "In a human asthma lung tissue model, the YTHDF1 gene binds to the cyclin 1 (CCND1) mRNA modification site, thereby stimulating the proliferation and migration of airway smooth muscle cells, which are involved in airway spasm and contraction during asthma pathogenesis." (PMID 39108751, 2024). "Collectively, these findings reveal a YTHDF1/cyclin D1 axis in asthma." (PMID 36992945, 2023). "To investigate the potential roel of m6A in asthma, we focused on a critical m6A reader YTHDF1." (PMID 36992945, 2023). "Collectively, these findings reveal a novel axis of YTHDF1/m6A/cyclin D1 in asthma’s airway remodeling, which may provide novel therapeutic strategy for asthma." (PMID 36992945, 2023). "Moreover, aberrant upregulation of YTHDF1 was observed in asthma patients compared to control subjects 144, therefore targeting YTHDF1 condensates may be a clinical strategy for improving allergic airway inflammation." (PMID 39239525, 2024). "Mechanistically, YTHDF1 significantly combined with cyclin D1 mRNA, thereby enhancing its mRNA stability through m6A-depedent pattern, which may provide novel therapeutic strategy for asthma." (PMID 36992945, 2023). "Thus, our assays’ data revealed the potential function of m6A reader YTHDF1 in asthma." (PMID 36992945, 2023). "Additionally, the m6A RNA modification machinery including METTL3, METTL14, FTO, YTHDF1/2, IGF2BP2, and WTAP is explored for its emerging significance in regulating post-transcriptional gene expression during asthma progression." (PMID 41008562, 2025). "Recent research demonstrates that the YTHDF1 reader protein is increased in PDGF-BB-induced airway smooth muscle (ASM) cells, promoting cell proliferation and migration, which are critical events in airway remodeling related to asthma." (PMID 41008562, 2025). "This enhancement of CLOCK translation by YTHDF1 is instrumental in the inflammatory process, as YTHDF1 further activates the NLRP3 inflammasome, leading to the production of IL‐1β, a key cytokine in asthma‐related airway inflammation." (PMID 41473388, 2025).
breast tumor (6 papers, 2020 to 2025). "In summary, our results indicate that YTHDF1 plays a key role in promoting breast tumor growth and metastasis in vivo, while miR-16-5p exhibits potential anti-tumor effects by selectively inhibiting YTHDF1." (PMID 35319018, 2022). "Several m6A regulators had significantly differential mRNA and protein expression in breast tumor and adjacent tissues, and m6A readers YTHDF1 and YTHDF3 might be good survival predictors." (PMID 34804948, 2021). "Moreover, YTHDF1 silencing also substantially reduced lung metastasis of breast tumors in mice." (PMID 35319018, 2022). "Furthermore, western blot revealed that the protein levels of METTL3, METTL14, and FTO were significantly lower in seven breast tumor samples randomly selected from RT-qPCR samples, while YTHDF1 and YTHDF3 had higher protein expression compared to adjacent tissues." (PMID 34804948, 2021). "We further examined the YTHDF1 and PKM2 expression levels in matched pairs of patient-derived breast tumor and adjacent normal tissue using Immunohistochemistry, of which the results showed that both YTHDF1 and PKM2 were upregulated in tumor tissues and supported the positive correlation in between." (PMID 35319018, 2022). "In Curtis database, YTHDF1 was overexpressed in invasive ductal carcinoma, invasive lobular carcinoma, mucinous carcinoma, and medullary carcinoma, but not in benign breast neoplasm." (PMID 35279688, 2022).
osteosarcoma (6 papers, 2021 to 2025). A usually aggressive malignant bone-forming mesenchymal neoplasm, predominantly affecting adolescents and young adults. "In line with the results for U2OS, we also observed similar effects of overexpressed YTHDF1 on cell proliferation and migration in another osteosarcoma cell line Saos2." (PMID 33431791, 2021). "Altogether, these results confirm that YTHDF1 regulates METTL3‐mediated PRKDC m6A modification, contributing to the maintenance of anlotinib resistance in osteosarcoma." (PMID 39924638, 2025). "We demonstrated that YTHDF1 knockdown decreased PRKDC mRNA and DNA‐PKcs protein levels and reversed the changes in osteosarcoma sensitivity to anlotinib induced by METTL3 overexpression." (PMID 39924638, 2025). "RIP assays demonstrated that YTHDF1 bound directly to PRKDC mRNA in MG63 cells and human osteosarcoma tissues." (PMID 39924638, 2025). "Based on two large-scale cohorts, HNRNPA2B1, HNRNPC, RBM15, YTHDF1, and YTHDC1 expression levels are upregulated in osteosarcoma tissues." (PMID 34094986, 2021). "Furthermore, FISH‐IF assays confirmed the co‐localisation of YTHDF1 protein and PRKDC mRNA in MG63 and U‐2 OS cells as well as in human osteosarcoma tissues." (PMID 39924638, 2025). "Hence, we hypothesised that YTHDF1 might serve as a ‘reader’ of PRKDC m6A methylation, thereby affecting the sensibility of osteosarcoma cells to anlotinib." (PMID 39924638, 2025).
pulmonary fibrosis (6 papers, 2023 to 2025). Chronic progressive interstitial lung disorder characterized by the replacement of the lung tissue by connective tissue, leading to progressive dyspnea, respiratory failure, or right heart failure. "H3K18la promotes the expression of the m6A reading protein YTHDF1, facilitating the progression of pulmonary fibrosis." (PMID 41199784, 2025). "Notably, the presence of H3K18 lactylation in pulmonary fibrosis was found to enhance the transcription of YTHDF1." (PMID 38202819, 2024). "In bleomycin‐treated mice, upregulated METTL3 has been identified to enhance the m6A modification of KCNH6 mRNA in a YTHDF1‐dependent manner to promote its translation and expression, which evokes the phenotypic conversion of alveolar myofibroblasts and pulmonary fibrosis." (PMID 37537731, 2023). "METTL3 promotes the YTHDF1-dependent translation of KCNH6, thereby accelerating EMT and myofibroblast proliferation, worsening idiopathic pulmonary fibrosis (IPF)." (PMID 41515964, 2025).
renal fibrosis (6 papers, 2022 to 2025). A final common manifestation of a wide variety of chronic kidney diseases characterized by glomerulosclerosis and tubulointerstitial fibrosis. "Research has shown that YTHDF1 is implicated in the progression of renal fibrosis and is highly expressed in human fibrotic kidneys." (PMID 40371338, 2025). "Beyond YTHDF1 and the YAP pathway, m6A-dependent regulation of PTEN has been implicated in renal fibrosis." (PMID 40895041, 2025). "Their experiments in mice and cultured cells supported the role of YTHDF1 in promoting renal fibrosis by regulating YAP." (PMID 39756462, 2025). "The m6A RNA methyltransferase METTL3 can enhance NSD2 mRNA stability and expression by YTHDF1 to alleviate renal impairment and renal fibrosis in DN." (PMID 35354439, 2022). "m6A RNA methylation was found to be significantly elevated in renal fibrosis, accompanied by increased expression of key m6A regulators, including METTL3, METTL14, ALKBH5, YTHDF1, and YTHDF3." (PMID 39756462, 2025). "Xing, He found that YTHDF1 expression was elevated in MCs cultured with TGF-β, and at the same time, the expression of the signature protein α-SMA in myofibroblasts was also increased, indicating that YTHDF1 in mesangial cells was involved in the renal fibrosis process." (PMID 37865763, 2023).
endometrial cancer (5 papers, 2018 to 2026). Primary or metastatic malignant neoplasm involving the endometrium (mucous membrane that lines the endometrial cavity). "FTO, RBM15, and YTHDF1, were identified as independent prognostic markers and closely associated with International Federation of Gynecology and Obstetrics grade in endometrial cancer patients." (PMID 34149936, 2021). "Additionally, several researchers have determined that in endometrial cancer, the YTHDF1 enhances the growth of tumors by controlling the ERK/NF‐κB/AKT signaling cascade via the PAPPA/IGFBP4 axis." (PMID 39821576, 2025). "Similarly, a recent study demonstrated that both of YTHDF1 and YTHDF2 were involved in regulating AKT signaling to promote the proliferation and tumorigenicity of endometrial cancer cells." (PMID 30787270, 2019).
leukemia (5 papers, 2020 to 2025). A malignant (clonal) hematologic disorder, involving hematopoietic stem cells and characterized by the presence of primitive or atypical myeloid or lymphoid cells in the bone marrow and the blood. "Consistently, the elevated YTHDF1 protein is detected in human acute myelogenous leukemia, and is concentrated in leukemia stem cells." (PMID 40986143, 2025). "YTHDF1 knockdown suppresses stemness maintenance, proliferative capacity, and leukemia-initiating ability in primary human/mouse leukemia stem cells." (PMID 40986143, 2025). "Tegaserod, an FDA-approved drug, is a YTHDF1 inhibitor that blocks YTHDF1 from directly binding to m6A-modified mRNA, inhibiting leukemia occurrence." (PMID 39062595, 2024). "Interestingly, research has found that decitabine can inhibit YTHDF1, thereby suppressing YTHDF1‐regulated translation and leukemia development." (PMID 39445003, 2024).
nasopharyngeal carcinoma (5 papers, 2021 to 2025). A carcinoma arising from the nasopharyngeal epithelium. "Knockdown of YTHDF1 via siRNA or reduction of SUMOylation of YTHDF1 or YTHDF3 by mutation of the SUMOylation sites during EBV reactivation in CNE2EBV cells (EBV-carrying poorly differentiated nasopharyngeal carcinoma cells) and Akata cells results in increased virus production." (PMID 39868828, 2025). "In EBV-induced nasopharyngeal carcinoma, YTHDF1 has been shown to inhibit tumor development by downregulating BZLF1 and BRLF1, thereby reducing the stability of EBV transcripts, and interact with the RNA degradation complex to promote RNA degradation." (PMID 34136491, 2021). "The m6A reader YTH domain-containing family protein 1 (YTHDF1) acts as an oncogene in multiple malignancies, yet its specific roles and regulatory mechanisms in nasopharyngeal carcinoma (NPC) have not been fully elucidated." (PMID 41167308, 2025).
pancreatic adenocarcinoma (5 papers, 2021 to 2022). "Our results showed that YTHDF1 expression had significant positive associations with TMB in LUAD, LUSC, BLCA, PAAD (pancreatic adenocarcinoma), SARC (sarcoma), BRCA, STAD, LGG, and ACC and negative relations in COAD and THCA." (PMID 34026603, 2021).
rectum adenocarcinoma (5 papers, 2021 to 2023). An adenocarcinoma arising from the rectum. "To clarify the differential expression in tumors, we further examined the YTH domain family and found that YTHDF1 was obviously elevated in rectum adenocarcinoma (READ), LIHC, CHOL and ESCA." (PMID 37833468, 2023).
cholangiocarcinoma (4 papers, 2021 to 2026). A carcinoma that arises from the intrahepatic biliary tree (intrahepatic cholangiocarcinoma) or from the junction, or adjacent to the junction, of the right and left hepatic ducts (hilar cholangiocarcinoma). "Meanwhile, we found that IGF2BP1/2/3 had higher expression levels than YTHDF1/2/3 in cholangiocarcinoma." (PMID 41513610, 2026).
gastric tumors (4 papers, 2022 to 2025). "The loss of YTHDF1 in gastric tumors potentiates the antitumor immune response by promoting the infiltration of mature dendritic cells." (PMID 39185313, 2024). "Consequently, the loss of YTHDF1 in tumor cells triggered collateral attack to gastric tumors, leading to tumor elimination." (PMID 35193930, 2022). "Herein, we aimed to determine the role of YTHDF1 in regulating gastric tumor immune microenvironment." (PMID 35193930, 2022). "Another potential strategy is to directly knockdown YTHDF1 in gastric tumors by in vivo siRNA to promote DCs infiltration and activation, thereby promoting antitumor immune response." (PMID 35193930, 2022). "In addition, depletion of YTHDF1 elevated sensitivity to antitumor immunity via recruitment of mature dendritic cells in gastric tumors." (PMID 36003776, 2022). "Second, YTHDF1 and TSC22D1 may serve as molecular biomarkers for stratifying EBV-positive versus EBV-negative gastric tumors or for predicting therapeutic response." (PMID 41472023, 2025).
HIV-1 infection (4 papers, 2016 to 2024). The type species of lentivirus and the etiologic agent of acquired immunodeficiency syndrome (AIDS). "Future studies using targeted mutations of the identified m6A sites in HIV-1 genome may lead to a loss of the effects on HIV-1 infection by YTHDF1–3 knockdown or overexpression." (PMID 27371828, 2016). "Overall, these data suggest that overexpression of YTHDF1–3 proteins significantly inhibits HIV-1 infection, while knockdown of these proteins efficiently promotes HIV-1 gene expression." (PMID 27371828, 2016). "We noticed a differential level of the effect on HIV-1 infection in different cell types by manipulating the individual YTHDF1–3 proteins." (PMID 27371828, 2016). "In contrast, stable knockdown of individual, endogenous YTHDF1–3 proteins in HeLa cells significantly increased HIV-1 infection by four- to 14-fold (p<0.05) relative to control cells." (PMID 27371828, 2016). "However, other studies have shown that YTHDF1/2/3 proteins inhibit HIV-1 infection by blocking viral reverse transcription and promoting viral RNA degradation, or by reducing viral gRNA and early reverse transcription products." (PMID 38238848, 2024). "It was revealed that upregulation of YTHDF1 in cells could contribute to reduced HIV-1 infection mainly by diminishing HIV-1 reverse transcription." (PMID 35508474, 2022). "In response to HIV-1 infection, the host may evolve and utilize the YTHDF1–3 proteins to bind the m6A-modified viral RNA and inhibit its reverse transcription and subsequent viral mRNA expression." (PMID 27371828, 2016). "Furthermore, knockdown of individual, endogenous YTHDF1–3 proteins in activated primary CD4+ T-cells from healthy donors enhanced HIV-1 infection by approximately two-fold (p<0.005), confirming the effects observed in cell lines despite a lesser extent." (PMID 27371828, 2016). "Thus, endogenous YTHDF1–3 proteins in CD4+ T-cells act as negative regulators to inhibit post-entry HIV-1 infection." (PMID 27371828, 2016). "Compared to vector control cells, at 24 hr post-infection (hpi), overexpression of individual FLAG-tagged YTHDF1–3 proteins in HeLa cells significantly inhibited HIV-1 infection by approximately 10-fold (p<0.0005) and drastically reduced the synthesis of full-length viral Gag protein (Pr55)." (PMID 27371828, 2016). "We found that the overexpression of YTHDF proteins in cells inhibited HIV-1 infection mainly by decreasing HIV-1 reverse transcription, while knockdown of YTHDF1–3 in cells had the opposite effects." (PMID 27371828, 2016). "Here, we show that YTHDF1–3 proteins recognize m6A-modified HIV-1 RNA and inhibit HIV-1 infection in cell lines and primary CD4+ T-cells." (PMID 27371828, 2016). "Indeed, we observed a unique high peak within the rev gene of HIV-1 RNA bound by YTHDF1, while YTHDF1 and YTHDF2 appear to have similar inhibitory effects on HIV-1 infection." (PMID 27371828, 2016).